EGFR (epidermal growth factor receptor)
Diseases named in the same sentence as EGFR in open-access papers (continued):
Sharing a sentence is not in itself a finding about the gene and the disease.
colon carcinoma (continued). "Subsequent investigations in colon cancer cells have suggested that the anticancer effects of dodecanoic acid may be partially mediated through the downregulation of the epidermal growth factor receptor, a pivotal player in apoptosis regulation and cancer cell survival." (PMID 39457508, 2024). "EGFR can activate a variety of downstream signaling pathways, which can induce subsequent biological effects, participate in the occurrence and development of colon cancer, and may affect tumor metastasis and prognosis." (PMID 37481519, 2023). "Therefore, it was suggested that the FOXD3 gene could inhibit the occurrence and progression of colon cancer bone metastatic cells by regulating the EGFR/ERK signaling pathway." (PMID 37151068, 2023). "However, this crosstalk may also restrict p38γ activity to phosphorylate and/or to enhance PTPH1 dephosphorylating oncogenic substrates such as EGFR to confer the phenotype of KRAS-mutant colon cancer resistant to EGFR inhibitors." (PMID 37443708, 2023). "Overall, this study demonstrated that the downregulation of the FOXD3 gene might promote the proliferation of colon cancer bone metastatic cell lines through the EGFR/ERK pathway and promote their migration through EMT, thereby serving as a promising therapeutic target." (PMID 37151068, 2023). "In colon cancer, somatic KRAS mutations, located mainly in codon 12 and 13 of exon 2, have been reported to lead to a more aggressive and invasive tumor and have been associated with resistance to anti-epidermal growth factor receptor (EGFR) monoclonal antibodies such as cetuximab and panitumumab." (PMID 36900260, 2023). "In addition, the downregulation of the FOXD3 gene in colon cancer bone metastatic cells could also affect the EGFR/ERK signaling pathway and alter the expression levels of EMT-related proteins." (PMID 37151068, 2023). "Colon cancer SW-480 cells were used to determine whether the apoptotic effect of rTBL-1 was related to its interaction with EGFR since SW-480 expresses a higher level of EGFR than HT-29 cells." (PMID 37259433, 2023). "As a possible mechanism of chemotherapy resistance in CRC, the authors proposed that shed SDC1 may interact with soluble heparin-binding EGF-like growth factor enhancing the activation of EGFR and downstream signaling, which in turn decreases the chemotherapeutical sensitivity of colon cancer cells." (PMID 36353562, 2022). "In in vivo colon cancer studies, conjugates of nanodiamonds with chemotherapeutic agents: ND-cisplatin and ND-cetuximab combined with monoclonal antibodies against the epidermal growth factor receptor (EGFR) showed selective binding of the conjugate to antibody-bearing cancer cells." (PMID 34361101, 2021). "In addition, SPRY2 might serve as a potential biomarker with respect to anti-EGFR treatment response in colon cancers." (PMID 34685612, 2021). "Microsatellite stable colon cancer models with BRAF or KRAS mutations in Subgroups II and IV have shown responses to the combination of EGFR (cetuximab), MEK (trametinib), and/or RAF (regorafenib) inhibition, providing a strong hypothesis for further evaluation." (PMID 34885128, 2021). "Anti-EGFR TKIs may help modulate that resistance with promising results in colon cancer." (PMID 33807612, 2021). "Furthermore, knockout of the EGFR pathway in the colon cancer cells reversed macrophage polarization back to a M1 subtype, suggesting that EGFR signaling of colon cancer cells modulates macrophage polarization and repolarization to promote colon cancer development and progression." (PMID 34063667, 2021). "Moreover, a previous study showed that the cellular cytotoxicity mediated by Cetuximab, an anti-epidermal growth factor receptor monoclonal antibody, could be inhibited by HLA-E membrane expression in colon cancer cells." (PMID 32066399, 2020). "In addition, activation of FXR abolished colon cancer cell growth by inhibiting EGFR/ERK signaling." (PMID 32807788, 2020).
colon carcinoma (continued). "Recently, Russo and colleagues provided evidence suggesting that colon cancer patients undergoing targeted therapy by inhibitors of EGFR (epidermal growth factor receptor) and/or BRAF (serine/threonine-protein kinase B-Raf) might also become resistant to these treatments by a similar mechanism." (PMID 32075223, 2020). "Furthermore, we provide evidence that HOXA5 short RNA may have activated EGFR signaling in both colon cancer cell lines and xenograft tumors." (PMID 31159758, 2019). "However, the decision to allow reimbursement appears to have been influenced by strong clinical evidence documented on the FDA drug label, suggesting that testing for overexpression of EGFR contributes to achieving an optimal therapeutic effect in both lung and colon cancers." (PMID 31427963, 2019). "BRAF genotypes are often assayed in colon cancer, either by immunohistochemistry or other molecular assays as activating BRAF mutations are also a relative contraindication to EGFR targeted therapy, and BRAF status may play an additional role in Lynch syndrome screening." (PMID 29698444, 2018). "Thus, targeting ERRα may be a potential novel therapeutic strategy to enhance the efficiency of EGFR signalling inhibition in colon cancer cells." (PMID 30185207, 2018). "Furthermore, proteoglycanpurified from P. linteus suppressed colon cancer by protecting T cells and disrupting the EGFR/AKT pathway, and inhibited SW480 colon cancer cell growth by G2/M phase arrest and suppressed tumor growth in a xenografted model by altering the Wnt/β-catenin pathway." (PMID 28800074, 2017). "Thus, it is of interest to further investigate whether FTD‐induced EGFR serine/threonine phosphorylation mediates similar prosurvival signaling through EGFR endocytosis in colon cancer cells." (PMID 28486761, 2017). "Moreover, we selected only left colon tumors as samples to rule out the bias from different locations of CRC, because the new NCCN guidelines of colon cancer have already mentioned that anti‐EGFR therapy has relatively lower benefits on the right‐sided colon compared with the left‐sided colon." (PMID 28745433, 2017). "Next, we examined whether IGF-1 levels in colon cancer CM were regulated by the EGFR pathway." (PMID 27683110, 2016). "To investigate whether EGFR signaling activity in colon cancer cells stimulates Ana-1 macrophage polarization and how this polarization affects tumor growth, we subcutaneously injected HCT116 or HCT116 KO-EGFR cells with or without Ana-1 cells into Balb/c athymic nude mice." (PMID 27683110, 2016). "However unlike HaCaT keratinocytes, loss of Dsg2 does not alter the total level of EGFR in SK-CO15 colon cancer cells." (PMID 26918609, 2016). "This suggests that colon cancer patients with BRAF (V600E) mutations, for whom there are currently no targeted treatment options available, might benefit from a combination therapy of BRAF and EGFR inhibitors." (PMID 26916442, 2016). "Considering rare data provided for NRAS mutations in stage II/III colon cancer, large population cohort investigation for this gene mutation detection should be performed, as NRAS closely related to KRAS and NRAS mutation was prognostic for EGFR MoAbs therapy inmCRC28." (PMID 27074743, 2016). "Interestingly, B-Raf mutant colon cancer cells already express significant levels of the EGFR." (PMID 27342992, 2016). "Additionally, a KRASG12D mutation was found in the colon carcinoma of Da236, which is a negative predictor of response to anti-epidermal growth factor receptor antibodies in today’s practice." (PMID 26252375, 2015). "Therefore, the combination of EGFR mAbs with chemotherapy could be effective for the treatment of colon cancer." (PMID 26491668, 2015).
colon carcinoma (continued). "To characterize EGFR downstream signaling that may correlate with the synergistic inhibitory effects of cetuximab and cisplatin on colon cancer cell growth, we examined whether combination treatment with cetuximab and cisplatin affected EGFR and its downstream signaling pathway." (PMID 26491668, 2015). "A colon cancer cell line with a BRAF V600E mutation was shown to escape vemurafenib inhibition by activating the epithelial growth factor receptor (EGFR); however, treatment of these cells with vemurafenib and an EGFR inhibitor prevented vemurafenib resistance and induced apoptosis." (PMID 25706985, 2015). "Co-expression of all members of the HER family in colon cancer supports the need for further investigations on their predictive value for response to therapy with anti-EGFR mAbs and whether such sub-population of patients may benefit from therapy with the new generation of pan-HER inhibitors." (PMID 24609222, 2014). "Thus, although our results reveal a new mechanism for berberine's action on EGFR that may be important for colon tumor prevention and treatment, further studies are needed to elucidate the mechanisms underlying berberine up-regulation of Cbl activation." (PMID 23457600, 2013). "Therefore, we hypothesized that DHA exerts its effect on colon cancer in part by altering the localization and signaling of EGFR." (PMID 22761867, 2012). "However, the prognostic effect of phospho-EGFR in primary colon cancer remains undefined." (PMID 19997103, 2010). "Additionally the existence of cross-talk between GPCR and EGFR signaling systems has been established in various cancer cells and has been found to promote cancer cell proliferation and migration through EGFR transactivation in colon cancer and renal cell carcinoma." (PMID 20723226, 2010). "Finally, one could even envision a combined approach where the addition of demethylation agents and OSM to anti-EGFR antibodies could target colon cancer cells and greatly diminish their chance of therapeutic escape." (PMID 19662090, 2009). "Interestingly, Arteaga and Baselga have noticed that EGFR-positive colon carcinomas with simultaneous expression of pEGFR, coexpressed the EGFR ligand transforming growth factor-α and markers of tumour proliferation, which is in contrast to EGFR-positive/pEGFR-negative carcinomas." (PMID 18522728, 2008). "Furthermore, combination therapy of NSAIDs and EGFR antagonists display an additive effect against colon tumor development in vivo and two previous studies suggest that NSAIDs might inhibit EGFR signaling." (PMID 16138927, 2005). "EGFR (epidermal growth factor receptor) signaling, a pathway often upregulated in CRC, represses HBD1 when activated in colon tumor tissue cell lines." (PMID 40585846, 2025). "In our study, the addition of anti-EGFR therapy to doublet chemotherapy resulted in numerically longer PFS and OS compared to anti-VEGF therapy in RAS/RAF wild-type right-sided colon tumors." (PMID 40428735, 2025). "Among patients with RAS/RAF wild-type right-sided colon tumors, PFS was comparable between those treated with anti-EGFR plus doublet chemotherapy and those receiving anti-VEGF plus doublet therapy." (PMID 40428735, 2025). "As mentioned, the EGFR/MAPK signaling pathway is involved in the oncogenic process and thus plays a key role in tumor growth and the progression of colon cancer." (PMID 41226554, 2025). "Herein, we verified the inhibitory effect of Hesperidin on colon cancer cell proliferation, migration, and invasion by downregulating SLC5A1 and inhibiting EGFR phosphorylation." (PMID 39781340, 2025). "The husk extract inhibited the growth of colon cancer cell lines HCT116 and HT29 through the EGFR pathway, as indicated by the gene expression data." (PMID 41226554, 2025). "Based on these observations, we propose that Hesperidin exerts its anticancer effects in colon cancer cells by downregulating SLC5A1 expression, which diminishes EGFR phosphorylation." (PMID 39781340, 2025).
colon carcinoma (continued). "In colon cancer, EGF secreted by colon cancer cells promotes the polarization of TAMs into M2 TAMs by binding to the EGF receptor (EGFR) on TAMs, which in turn activates the AKT signaling pathway." (PMID 39889181, 2025). "The dose-dependent effect of SPINK4 on phosphorylated EGFR (Y1608) was measured in the intestinal cell line NCM460 and colonic cancer cell line HT-29." (PMID 38997284, 2024). "In a colon cancer cell line model, the presence of ephrinA5 exerted an inhibitory effect on EGFR by facilitating c-CBL-mediated EGFR ubiquitination and subsequent degradation." (PMID 39130630, 2024). "We demonstrate dynamic evolution of resistance to combined EGFR/BRAF/MEK inhibition in a pediatric patient with metastatic BRAF-V600E-mutant, mismatch repair-stable colon cancer." (PMID 39626159, 2024). "It is also likely that EGFR is one of the target molecules for the rTBL-1, and many other membrane glycoproteins could be interacting, as aberrant sialylation and fucosylation are common in other glycoproteins involved in the development of many types of cancers, including colon cancer." (PMID 39769023, 2024). "In a model of colon cancer, SMARCA4 and PRMT1 were shown to promote CRC progression cooperatively via EGFR signaling." (PMID 38472198, 2024). "The metastatic behavior of colon cancer cell lines is enhanced by Gal-3 in a carbohydrate-dependent manner through the EGFR/K-Ras–Raf–ERK pathway and is blocked by the EGFR inhibitor cetuximab." (PMID 38570874, 2024). "A network reconstructed from the selected functions shows a strong integration with the functions involved in colon cancer and melanoma, namely AKT1, EGFR and MAPK3." (PMID 37629086, 2023). "Therefore, this study suggested that the FOXD3 gene might inhibit the development of EMT and regulate the proliferation of colon cancer bone metastasis cells through the EGFR-RAS-Raf-MEK-ERK signaling pathway, thereby exhibiting a potential for novel future therapies." (PMID 37151068, 2023). "Firstly, in 2002, it was demonstrated that PGE2 promotes EGFR phosphorylation and triggers the ERK2 signaling pathway in normal gastric epithelial and colon cancer cell lines." (PMID 37190301, 2023). "Due to the abundance of EGFR on the surface of colon tumor cell lines, it was altered using PEG and a specific monoclonal antibody against EGFR (cetuximab)." (PMID 36866455, 2023). "In this study, we report on the effect of deacetylated Sia on the activity of three novel EGFR-targeting Cucurbitacin-inspired estrone analogs (CIEAs), MMA 294, MMA 321, and MMA 320, in lung and colon cancer cells." (PMID 37687086, 2023). "Interstingly, a compound with a similar structure of midazolam named 3-indolyl cyclopent[b]indoles is known to inhibit EGFR pathway in NSCLC cells and colon cancer cells." (PMID 37305523, 2023). "Collectively, these findings support the conclusion that EGFR, ERK, and p38 MAPK activation play a role in McN-A-343-mediated inhibition of colon cancer cell proliferation." (PMID 37835460, 2023). "Despite accumulating evidence suggests that the EGFR or transforming growth factor α (TGFα)/ EGFR signaling pathways play a critical role in colon cancer progression, the EGF autocrine loop in colon cancer is still poorly investigated." (PMID 37853459, 2023). "This leads to increased EGFR protein expression (due to p38γ) and enhanced EGFR de-phosphorylation (due to PTPH1), resulting in a phenotype of increased levels of un-phosphorylated EGFR proteins in KRAS-mutant colon cancer cells." (PMID 37443708, 2023). "Cheng et al12 has revealed that BAs stimulate proliferation of H508 colon cancer cells which co-express both CHRM3 and EGFR." (PMID 36919835, 2023). "They found that the levels of IL-10 and arginase-1 increased, indicating that the colon cancer cells were involved in the M2 polarization of THP-1, which was also confirmed by using the EGFR antibody mAb225 and the PI3K inhibitor LY294002." (PMID 36709284, 2023).
colon carcinoma (continued). "We have also found that GALNT2 was able to mildly regulate the phosphorylation of EGFR and MET in colon cancer cells." (PMID 36409270, 2023). "Therefore, the analysis of EGFR and RAS/BRAF mutations in plasma using the IdyllaTM platform is feasible and reliable in clinical practice and allows the selection of the best treatment for our patients, especially those with metastatic lung adenocarcinomas and colon cancer." (PMID 36497340, 2022). "In the presence of EGFR, MDM2 can bind to peroxisome proliferator-activated receptor-gamma (PPARγ) and regulate the ubiquitination of PPARγ protein in colon cancer cells." (PMID 36230661, 2022). "Dual inhibition of EGFR and VEGFR was also tested in colon cancer, cutaneous squamous cell carcinoma, follicular thyroid cancer, oral cancer, orthotopic ovarian carcinoma, and prostate cancer." (PMID 35409206, 2022). "It has been documented that after addition of EGFR, MDM2 can bind to PPARγ and regulate the ubiquitination of PPARγ protein in colon cancer, and that MDM2 silencing can increase the level of PPARγ, which is further verified in bladder cancer." (PMID 36230661, 2022). "For colon cancer, identified biomarkers are CD15, CD104, CD324, CD326, CD49f, and for renal cancer, CD24, CD26, CD106 (VCAM1), EGFR, SSEA-3 (B3GALT5), SSEA-4 (TMCC1), TIM1 (HAVCR1), and TRA-1-60R (PODXL)." (PMID 36221114, 2022). "Nicotine exposure leads to higher phosphorylation of epidermal growth factor receptor (EGFR) and increased expression of 5-LOX in colon cancer." (PMID 35406504, 2022). "Non-small lung cancer H1299 and colon cancer HCT116 are at least two-times more sensitive to MGL S3 compared to MGL tetani, highlighting the increased dependency of these cells on EGFR." (PMID 36361596, 2022). "CDX2 status, EGFR status, tumour size, tumour location and lymph node ratio (LNR) were ranked of lowest importance in determining prognosis in colon cancer." (PMID 35323316, 2022). "More specifically, the cetuximab/cisplatin combination was shown to block the EGFR pathway via the inhibition of EGRF and ERK phosphorylation in the HCT116 and SW480 human colon cancer cell lines." (PMID 36139440, 2022). "Specifically, EGCG prevents the activation of the epidermal growth factor receptor (EGFR), the human epidermal growth factor receptor 2 (HER2), and a number of other signaling pathways that are downstream in colon cancer cell lines." (PMID 36142616, 2022). "While α2,6-sialylation supported adhesion and migration of colon cancer cells and metastatic spread, ST6Gal I knockdown in colon cancer cells SW480 was shown to lead to EGF-induced phosphorylation of EGFR and ERK activation." (PMID 34069424, 2021). "This causes a significant increase of EGFR dimerization, activation, and signaling in the EGFR response to EGF binding in human breast and colon cancer cells." (PMID 34944925, 2021). "Simultaneous activation of PKC/p38 and EGFR/ERK signaling potentiates MMP-1 gene and protein expression, and augments colon cancer cell invasion while blocking MMP-1 activity abolishes M3R agonist-induced colon cancer cell invasion." (PMID 34203220, 2021). "Cost-effectiveness comparison of chemotherapy + anti-EGFR mAb vs. chemotherapy + bevacizumab in (a) KRAS wild-type (b) pan-RAS wild-type and (c) pan-RAS wild-type left-sided colonic tumor." (PMID 34012917, 2021). "In colon cancer, PRMT1 is involved in epidermal growth factor receptor methylation during the resistance to cetuximab treatment." (PMID 34155784, 2021). "In this study, we established a novel proteomic signature (including EGFR, IGFBP2, SRC and SRC_pY527) for prognostic prediction of colon cancer using TCPA database." (PMID 33758598, 2021). "Upregulation of the IGF1R pathway constitutes a common paradigm shared with other receptor tyrosine kinases such as EGFR, HER2, and MET in different cancer types, including colon cancer." (PMID 34065119, 2021).